DAB2 (DAB adaptor protein 2)
Diseases named in the same sentence as DAB2 in open-access papers (continued):
Sharing a sentence is not in itself a finding about the gene and the disease.
breast tumours (1 paper, 2010). "In human breast tumours, loss of Dab2 protein expression was observed in 74% of samples analyzed, whereas expression in 10 normal breast tissue samples was maintained." (PMID 21063401, 2010). "Our results are thus consistent with a previous study, which determined that Dab2 protein levels were decreased in 74% of breast tumour samples examined." (PMID 21063401, 2010). "Decreased Dab2 protein expression has been shown in human breast tumours by immunohistochemistry; however, the antibody utilised does not discriminate between the two isoforms." (PMID 21063401, 2010). "Decreased expression of the p96 and p67 isoforms of Dab2 is observed in human breast tumour samples in comparison to normal human breast tissue." (PMID 21063401, 2010).
chlamydial infection (1 paper, 2015). "The loss of Dab2 during chlamydial infection will favor EMT, loss of epithelial polarity and function, and tumor promotion." (PMID 26681200, 2015).
chronic kidney disease (1 paper, 2022). Impairment of the renal function secondary to chronic kidney damage persisting for three or more months. "However, some targets remain unexplored for the DAB-2 gene in the TGF-β pathway in chronic kidney disease." (PMID 35127957, 2022).
Cirrhosis (1 paper, 2023). A chronic disorder of the liver in which liver tissue becomes scarred and is partially replaced by regenerative nodules and fibrotic tissue resulting in loss of liver function. "Our results showed that several crucial drivers, including regulators that are potentially associated with the progression of cirrhosis, such as SLC40A1, DAB2, FOLR2, GPAT3, and CDA, were upregulated during fibrosis." (PMID 36845083, 2023).
colon cancer (1 paper, 2023). "Previous studies established a decrease in DAB2 expression as a hallmark in a wide range of human tumors, including ovarian, breast, lung and colon cancer, and choriocarcinoma." (PMID 37510211, 2023). "In 736 samples of colon cancer, lower DAB2 gene expression was found in R-CRC compared to L-CRC (p < 0.0001)." (PMID 37510211, 2023). "Although DAB2 has long been known as a tumor suppressor in colon cancer, its predictive and prognostic potential is still insufficiently investigated." (PMID 37510211, 2023). "However, role for DAB2 protein in colon cancer is still not completely understood and further research is needed to prove its tumor suppressor potential." (PMID 37510211, 2023). "The expression of the suppressor gene DAB2 in colon cancer has already been analyzed, but its significance has not been fully elucidated." (PMID 37510211, 2023).
colorectal adenocarcinoma (1 paper, 2023). The most common type of colorectal carcinoma. "Immunohistochemistry was performed to explore DAB2 expression in terms of the normal colon resection margin and corresponding colorectal adenocarcinoma." (PMID 37510211, 2023).
deafness (1 paper, 2016). An inherited or acquired condition characterized by the complete loss of the ability to hear from one or both ears. "An myosin VI mutation (3496C > T) that causes deafness in Pakistani families leads to a premature stop in the C-terminal cargo-binding tail domain (at R1166X) and loss of the WWY motif, the binding site for myosin VI adaptor proteins, including Dab2, LMTK2 and Tom1/L2." (PMID 27474411, 2016).
diabetic nephropathy (1 paper, 2023). "They found that SNPs in Dab2 were associated with diabetic nephropathy." (PMID 37361044, 2023).
ductal carcinoma in situ (1 paper, 2014). "Of note, the expression of Dab2 was also diminished in ductal carcinoma in situ with microinvasion." (PMID 24638085, 2014).
embryonal carcinoma (1 paper, 2017). A non-seminomatous malignant germ cell tumor characterized by the presence of large germ cells with abundant cytoplasm resembling epithelial cells, geographic necrosis, high mitotic activity, and pseudoglandular and pseudopapillary structures formation. "F9 and P19 embryonal carcinoma cells respond to RA by increasing the levels of DAB2, and KERATIN 8/18, which we confirmed by immunoblot analysis." (PMID 29119099, 2017).
epithelioid mesothelioma (1 paper, 2022). "DAB2 positivity for epithelioid mesothelioma was 80–98% compared with 3–23% inpulmonary adenocarcinoma." (PMID 36614139, 2022).
experimental autoimmune encephalomyelitis (1 paper, 2013). An autoimmune demyelinating disease of the central nervous system that is produced experimentally in animals by the injection of homogenized brain or spinal cord in Freund's adjuvant. "Furthermore, dab2-deficient mice have a less severe experimental autoimmune encephalomyelitis disease course and suffer less neuroinflammation and less axonal injury than their wild-type littermates." (PMID 24252604, 2013). "We demonstrate that dab2 expression is positively correlated with experimental autoimmune encephalomyelitis disease severity during the acute disease phase." (PMID 24252604, 2013).
fetal growth restriction (1 paper, 2016). A fetus that does not grow beyond the 10th percentile of conventionally accepted weight for gestational age. "Results demonstrate that PM is associated with reduced syncytiotrophoblast abundance of megalin and Dab2 proteins, known to provide endocytosis and signaling pathways, which, in turn, may play a role in fetal growth restriction and low birth weight pathology." (PMID 27072056, 2016).
fibrosarcoma (1 paper, 2022). A malignant mesenchymal fibroblastic neoplasm affecting the soft tissue and bone. "CSF-1 enhanced DAB2 expression in TAMs isolated from MN-MCA1 fibrosarcoma mice models only in adherent conditions." (PMID 36614139, 2022).
gastritis (1 paper, 2024). Inflammation of the stomach. "Our results indicated that DAB2 expression was higher in 24 H pylori-positive gastritis samples than that in 8 H pylori-negative normal samples from the GSE60427 database." (PMID 38481347, 2024).
glaucoma (1 paper, 2020). Increased pressure in the eyeball due to obstruction of the outflow of aqueous humor. "Interestingly, we found 8 genes (FN1, THBS1, EPHB2, FGF2, DAB2, CD9, PLAUR and ITGA4) were crucial, suggesting that these genes might function as key factors in the pathogenesis of glaucoma." (PMID 31680442, 2020).
hydatidiform mole (1 paper, 2025). A gestational trophoblastic disorder characterized by marked enlargement of the chorionic villi, hyperplasia of the villous trophoblastic cells and hydropic changes. "Complete hydatidiform mole is associated with the DAB2 and ENPEP genes." (PMID 40565366, 2025).
Insulin resistance (1 paper, 2025). Increased resistance towards insulin, that is, diminished effectiveness of insulin in reducing blood glucose levels. "It was found that EC-specific Dab2 deficiency led to more severe insulin resistance and higher blood glucose compared with WT mice." (PMID 39846251, 2025).
liver cancer (1 paper, 2024). An epithelial or non-epithelial malignant neoplasm that arises from the liver. "The findings indicate that DAB2+ / SPP1+ TAMs are the dominant TAMs in liver cancer, and SPP1+ TAMs have been reported to be involved in the pro-tumor microenvironment in several studies 15, 56, 71-73." (PMID 39239526, 2024). "In conclusion, our findings indicate that DAB2+ and SPP1+ macrophages are the dominant TAMs in liver cancer." (PMID 39239526, 2024).
lymph node metastasis (1 paper, 2018). "Low expression of Dab2 is not correlated with the patients’ age (P = 0.8692), gender (P = 0.5747) or histological classification (P = 0.5991), but has a close relationship with the differentiation (P < 0.0001), TNM stage (P = 0.006194) and lymph node metastasis (P = 0.00004)." (PMID 30547821, 2018).
malaria (1 paper, 2016). Malaria is a serious and sometimes fatal disease caused by a parasite that commonly infects a certain type of mosquito which feeds on humans. "The abundance of both megalin and Dab2 was reduced in the syncytiotrophoblast brush border in malaria-infected placentas by indirect fluorescence microscopy, with statistical significance for both proteins." (PMID 27072056, 2016). "Abundance of both megalin and Dab2 is substantially reduced in the brush border of malaria-infected placentas obtained from LBW deliveries, with statistical significance for Dab2 (p = 0.046)." (PMID 27072056, 2016). "When data were stratified by the presence of placental inflammation in malaria-infected samples (n = 3) against samples without infection and inflammation, a similar decrease in megalin and Dab2 abundance was observed, with statistical significance for Dab2." (PMID 27072056, 2016).
medulloblastoma (1 paper, 2023). A malignant, invasive embryonal neoplasm arising from the cerebellum. "Of these seven genes (LTBP1, MAP1A, MBNL2, LGALS1, PNRC1, DAB2, and PLAAT3), only one, LGALS1, had been researched previously in relation to medulloblastoma, where it is up-regulated in MBSHH patients and activated by the SHH signalling pathway." (PMID 36831428, 2023).
metastatic cancers (1 paper, 2023). A carcinoma which has spread from the original site of growth to another anatomic site. "We assessed the proportion of DAB2+, CD68+ and double labelled (DAB2+ CD68+) cells in matched HGSOC patient tissues from primary and metastatic cancers." (PMID 37815603, 2023).
myelodysplastic syndrome (1 paper, 2025). A clonal hematopoietic disorder characterized by dysplasia and ineffective hematopoiesis in one or more of the hematopoietic cell lines. "DisGeNET data reveal associations between myelodysplastic syndrome and the genes CD36, DAB2, ENPEP, and TIMP1." (PMID 40565366, 2025).
myelogenous leukemia (1 paper, 2014). "Among them, DAB2 and Myc have been implicated in the progression of myelogenous leukemia." (PMID 24736311, 2014).
myeloid malignancy (1 paper, 2018). "Despite a clear defect in HSC maintenance, a subset of mice with constitutive marrow DAB2 expression developed a transplantable myeloid malignancy at a median of 34 weeks post transplant with a penetrance of approximately 30%." (PMID 29925839, 2018). "Taken together, these data suggest that DAB2 inhibits LT-HSC activity, but in parallel promotes myeloid progenitor activity, and that in some mice secondary events lead to myeloid malignancy that may be initiated in hematopoietic progenitor cells." (PMID 29925839, 2018).
myeloma (1 paper, 2016). "Interestingly, the DAB2 gene, which is common to all three GO pathways, has been reported to be a putative tumor suppressor whose hypermethylation could contribute to activation of Wnt signaling in myeloma." (PMID 27224915, 2016).
pancreatic adenocarcinoma (1 paper, 2019). "In support of this hypothesis, interrogation of the pancreatic adenocarcinoma TCGA cancer genomic dataset identified that Dab2 mRNA levels were higher in patient tumor samples designated as disease-free versus those whose disease had recurred or progressed." (PMID 31101868, 2019).
preeclampsia (1 paper, 2024). Preeclampsia is a hypertensive disorder of pregnancy that is characterized by new-onset hypertension with proteinuria presenting after 20 weeks of gestation, and depending on mild or severe forms may initially present with severe headache, visual disturbances, and hyperreflexia. "Our findings not only illuminate a novel aspect of DAB2 function but also hint at its broader implications in vascular biology and preeclampsia management." (PMID 38613672, 2024).
renal carcinoma (1 paper, 2013). A carcinoma arising from the epithelium of the renal parenchyma or the renal pelvis. "Thus, the variation of the relative abundance of DAB2 splice variants (i.e., p96 and 67) could be considered for further analysis to determine the functional relevance of this alteration in renal cancer, as these isoforms have non-overlapping cellular activities." (PMID 24194935, 2013).
renal fibrosis (1 paper, 2023). A final common manifestation of a wide variety of chronic kidney diseases characterized by glomerulosclerosis and tubulointerstitial fibrosis. "Taken together, for the last part, we reviewed the recent studies on the cytokines like TGFβ1 and Angiotensin II and genes such as Dab2, Rab7, and Manba, affecting tubular endocytosis, eventually causing renal fibrosis." (PMID 37799275, 2023).
retinal degeneration (1 paper, 2019). Degeneration of the retina. "We envisage that increased association between LCN-2 and Dab2 decreases integrin β1 internalization, which in turn increases the extracellular level of the integrin, activating transmigration into the retina and potentiating retinal degeneration." (PMID 31552301, 2019).
Sepsis (1 paper, 2016). Sepsis is defined as life-threatening organ dysfunction caused by a dysregulated host response to infection. "The newly identified link between Dab2 and the TRIF-dependent inflammatory response opens additional avenues to explore the immunological function of Dab2 and the therapeutic targets of endotoxin-induced sepsis." (PMID 27748405, 2016).
tumor (92 papers, 2005 to 2025). "Although this phenomenon has been strictly reported in tumor-associated macrophages, there is the potential that the DAB2 fusion protein remodels the extracellular matrix in the higher stromal microenvironment of ILC cell lines." (PMID 39207954, 2024). "DAB2-positive tumor-associated macrophages remodel the extracellular environment and are associated with overall poor clinical outcome in ILC." (PMID 39207954, 2024). "DAB2 is highly expressed in tumor-infiltrating tumor-associated macrophages (TAMs) and its downregulation significantly inhibits lung metastasis by regulating integrin recycling and extracellular matrix (ECM) remodeling." (PMID 38481347, 2024). "Dab2 gene polymorphism has been widely studied, and has found to be associated with some tumor diseases." (PMID 37361044, 2023). "In the tumor associated stroma, the proportion of DAB2+ (fold change 4.64, p = 0.029), CD68+ (fold change 2.04, p = 0.02) and DAB2+ CD68+ (fold change 3.15, p = 0.028) was significantly increased in metastatic compared to matched primary tumors." (PMID 37815603, 2023). "Amongst the proteins associated with malignancy, cell proliferation and cancer poor prognosis was disabled homolog 2 (Dab2) that was reported to be associated with epithelial-mesenchymal transition and tumor aggressiveness in BUC." (PMID 36148227, 2022). "Our review highlights how DAB2 in the majority of cases is associated with tumour suppressive phenotypes and hence is commonly downregulated." (PMID 36614139, 2022). "In oesophageal cancer, low DAB2 expression was associated with reduced overall survival (OS), increased risk of recurrence, larger tumour size, advanced stage of disease and metastasis." (PMID 36614139, 2022). "Loss of DAB2 is primarily associated with activation of these pathways and tumour progression, however this review also explores studies which demonstrate the complex nature of DAB2 function with pro-tumorigenic effects." (PMID 36614139, 2022). "These tumours had a lack of zonal structure, loss of medullar cells and high expression of the ZG marker Dab2 throughout the tumour." (PMID 33214683, 2021). "Our findings suggested that DAB2 expression was associated with poor prognosis through increased oncogenic properties including tumor proliferation, migration, invasion, and enhancement of EMT in human UCB." (PMID 31968685, 2020). "In earlier reports, DAB2 was considered to be a tumor suppressor gene due to its low expression and loss in several tumor cells." (PMID 31968685, 2020). "Higher expression of DAB2 was associated with higher clinical T category, high tumor grade, and poor oncological outcome." (PMID 31968685, 2020). "DAB2 expression both in cancerous and stromal lesions was associated with poor prognosis through increased oncogenic properties including tumor proliferation, migration, and invasion in human UCB." (PMID 31968685, 2020). "A novel tumour suppressive role for Dab2 was discovered using Dab2-floxed OSE where loss of Dab2 allowed KRASG12D over-expressing OSE cells to bypass OIS." (PMID 29196616, 2017). "Cellular analyses have suggested several diverse functions for the widely expressed proteins, and Dab2 is also considered a tumor suppressor, as loss or reduced expression is found in several cancer types." (PMID 27933291, 2016). "Together with the up-regulation of TGF-β expression and secretion, a compromised depletion of TGF-β in surrounding medium due to the loss of Dab2 contribute to the accumulation of TGF-β in the tumor microenvironment." (PMID 24638085, 2014). "Intriguingly, parallels drawn from oncological studies in which DAB2 expression was associated with tumor progression suggest that DAB2 may play a unique role in promoting cell viability and migration." (PMID 38613672, 2024).